IL6 (interleukin 6)
Diseases named in the same sentence as IL6 in open-access papers (continued):
Sharing a sentence is not in itself a finding about the gene and the disease.
Sepsis (continued). "In this way, we identified 38 biomarker genes, including IL6, SOCS3, and IRG1 which were already associated to sepsis by other studies." (PMID 25814982, 2015). "The activation of ERK1/2 and NF‐κB is critical for the production of inflammatory cytokines such as TNF-α and IL-6, during endotoxemia or sepsis." (PMID 25929655, 2015). "Fifteen studies reported that IL-6 appeared to be an indicator for sepsis or for predicting outcome/mortality." (PMID 26502877, 2015). "Here, we also found a ghrelin dependent, systemic suppression of IL-6 levels starting within the first 6h after sepsis induction." (PMID 25844479, 2015). "In models of murine melioidosis, it has been established that increased expression of IL-1β and IL-6 follow B. pseudomallei dissemination and coincide with acute sepsis and mortality." (PMID 26114445, 2015). "Increases in systemic inflammatory cytokines, such as IL-6 and TNF-α, are biomarkers for and causes of poor prognosis in sepsis." (PMID 25625512, 2015). "In contrast, in sepsis patients during the first 4 days of the ICU stay there was a time-dependent decline in plasma IL-6, IL-8 and IL-10 (P <0.0001 for all analytes), which are well-known cytokine markers in sepsis." (PMID 26603530, 2015). "Cytokine IL-6 enabled a significant differentiation between sepsis and fungemia, sepsis and viremia, and sepsis and bacteremia." (PMID 26315105, 2015). "The IL-1 β and IL-6 mRNA expression in Raw 264.7 cells were highly elevated after stimulation by burn sepsis serum." (PMID 26550025, 2015). "These biomarkers are all thought to participate in various components of the early patient responses to sepsis: early innate immune responses (IL-6, sTNF-R1) and inflammatory cell differentiation and recruitment (G-CSF and IL-8)." (PMID 26492036, 2015). "A similar study also showed that difficult to culture microbial taxa are present in amniotic fluid and this related to higher levels of IL-6, chorioamnionitis, funisitis and early onset sepsis." (PMID 27057323, 2015). "The significant increase in CK, LDH, TNF-α and IL-6 levels in the culture supernatant indicated that the H9C2 cell model of sepsis had been successfully constructed." (PMID 25873251, 2015). "Oxiris has been shown previously in a pig model of sepsis to decrease plasma IL-6 concentrations and improve cardiovascular function in agreement with the data presented in the current study." (PMID 25937432, 2015). "The significant increase in the levels of CK, LDH, TNF-α and IL-6 in our study indicated that the H9C2 cell model of sepsis had been created successfully." (PMID 25873251, 2015). "In mechanistic study, MT-2 upregulated the pAkt to Akt ratio and abrogated the increase of IL-1 β and IL-6 mRNA expression from macrophages that stimulated with burn sepsis serum." (PMID 26550025, 2015). "C5L2 has been shown to play a proinflammatory role during sepsis through intracellular signaling, release of cytokines IL-6, tumor necrosis factor α (TNF-α), and high mobility group box 1(HMGB1)." (PMID 24740152, 2014). "Serum levels of IL-6 and TNF-α are increased in systemic inflammatory response syndrome and sepsis patients and are associated with increased mortality." (PMID 24651840, 2014). "Although the levels of TNF-α and IL-10 declined towards normal from 8 to 24 hours of sepsis, the increase in IL-6 was maintained throughout the septic period indicating a maintained hyper-inflammatory phase." (PMID 25413250, 2014). "It was interesting to notice that IL-10 was higher in patients with severe sepsis, while IL-6 was similar between patients with severe sepsis and simple sepsis." (PMID 24977412, 2014). "Serum concentrations of Resistin, NGAL, IL-6 and IL-10 were higher in all sepsis cases compared to healthy controls (p≤0.003 for all comparisons, Mann Whitney)." (PMID 25343379, 2014).
Sepsis (continued). "Sepsis is caused by a systemic response to infection, which is characterized by elevated levels of proinflammatory cytokines such as TNF-α, IL-1β, IFNγ and IL-6 in the circulation or in inflamed tissues." (PMID 25269519, 2014). "The plasma eHSPA12B was also linearly correlated with the IL-6 level, which was a marker of sepsis severity." (PMID 24977412, 2014). "The cytokine response to sepsis has been well documented, with IL-6 suggested as an early marker and a marker of severity." (PMID 25398383, 2014). "Bilirubin is a break-down product of heme whose biliary excretion is counteracted by intrahepatically produced IL-1 and IL-6 in sepsis, while alpha-fetoprotein is produced in the regenerating liver following hepatitis or intoxication." (PMID 24642872, 2014). "Analysis of cytokine levels by multiplex array showed a rapid, sustained, and significant increase of the putative markers of experimental sepsis, namely IL-1β, IL-6, IL-10, and TNF-α, in FIP mice over a 24-hour period (p < 0.001) versus the sham group." (PMID 24725742, 2014). "The percentage of interphase neutrophil MDSC in sepsis patients is proportional to disease severity and correlates with plasma IL-6 concentrations." (PMID 25084831, 2014). "Independent risk factors for HHH identified by logistic regression analysis were hematological diseases, ≥15 % bone marrow macrophages, sepsis, and high IL-6 levels." (PMID 24852692, 2014). "Severe pneumonia patients treated with Xuebijing have shown decreased secretion of TNF-α, IL-6 and IL-8, similarly to patients with sepsis." (PMID 25511395, 2014). "• Decreased survival and persistent elevation of serum IL-6 levels was observed in severe sepsis in elderly patients and aged septic mice." (PMID 24962182, 2014). "Systemic elevations in serum procalcitonin and IL-6 levels were also seen in patients with severe sepsis." (PMID 25722876, 2014). "IL-6 has been suggested to be an early inflammatory marker, and levels correlate well with the severity and prognosis of sepsis." (PMID 24696530, 2014). "The serum IL-6 concentration was consistently higher in elderly sepsis patients than in adult sepsis patients; the mean difference between the groups was 354 to 13,095 pg/mL (P <0.01)." (PMID 24962182, 2014). "ApoE inhibited the lipopolysaccharide (LPS)-induced increase of tumor necrosis factor-α, interleukin (IL)-1β and IL-6 in serum and decreased the mortality rates of mice with sepsis." (PMID 25242054, 2014). "They observed high (>1.000 pg/mL) values in most individuals included in the sepsis group as well as a notable increase in IL-6 concentration in postmortem serum compared with IL-6 levels in antemortem samples." (PMID 24778096, 2014). "Several studies have demonstrated that serum IL-6 levels are adiagnostic and prognostic biomarker for sepsis patients." (PMID 24303815, 2014). "PCT best predicted septicemia when compared with IL-6 and CRP with 73% sensitivity and 70% specificity for bacteremia with a cutoff of 0.5 ng/mL." (PMID 24772418, 2014). "Tumor necrosis factor-α, and IL-6 are two key cytokines involved in tissue damage during sepsis, although it has been suggested that TNF-α is the central mediator regulating other subsequent events." (PMID 25312795, 2014). "As an immunomodulator, visfatin induces dose-dependent up-regulation of the pro- and anti-inflammatory cytokines, IL-1β, IL-6, IL-10, and TNF-α in human monocytes: visfatin is associated with sepsis, acute lung disease, atherosclerosis, and cancer." (PMID 24885580, 2014). "The presence of endotoxin in the blood stream is a primary contributor of septic shock, and several proinflammatory cytokines such as TNF-α and IL-6 can contribute to cardiac dysfunction during sepsis." (PMID 25180179, 2014). "First, it was demonstrated that measurements of presepsin levels had valuable and consistent diagnostic capacity for the different stages of sepsis severity compared to PCT, IL-6, CRP and WBC during the first week of ICU treatment." (PMID 25190134, 2014).
Sepsis (continued). "Compared with the control group, the inflammatory cytokine levels of IL-2, IL-6 and IL-10 in patients with sepsis or intracranial infection were significantly elevated (both P<0.05)." (PMID 24887408, 2014). "The characteristic cytokine markers of sepsis, including IL-1β, IL-6, IL-10 and TNF-α, increased significantly during the experimental timeline." (PMID 24725742, 2014). "Mice which received the siRNA injection demonstrated lower levels of IL-17 and IL-6 compared with the Sc injection group and the sepsis group at 6 h." (PMID 24913772, 2014). "As analyzed above, CRP and the three cytokines IL-2, IL-6 and IL-10 were differentially related to sepsis and intracranial infection." (PMID 24887408, 2014). "IL-6 is an early inflammatory mediator that is markedly upregulated in the serum of patients with sepsis." (PMID 24940428, 2014). "The relationship between eHSPA12B and prognosis of severe sepsis was analyzed in comparison with IL-6 and IL-10." (PMID 24977412, 2014). "The serum IL-6 concentrations were consistently higher in the aged sepsis group than in the young sepsis group; the mean difference between the groups was 11,514 to 28,870 pg/mL (P <0.01)." (PMID 24962182, 2014). "The percentage of interphase neutrophils in sepsis was proportional to sepsis severity and correlated with plasma IL-6 concentrations." (PMID 25084831, 2014). "The area under the curve (AUC) of eHSPA12B in predicting death among patients with severe sepsis was 0.782 (0.654–0.909) in ROC analysis, much higher than that of IL-6 and IL-10." (PMID 24977412, 2014). "The levels of IL-8, IL-6, and monocyte chemoattractant protein-1 (MCP-1) are associated with early 48-hr and 28-day mortality in sepsis patients." (PMID 24886652, 2014). "In patients with suspected severe sepsis and septic shock, precipices reveals valuable diagnostic capacity to differentiate sepsis severity compared to PCT, IL-6, CRP, WBC." (PMID 25190134, 2014). "The sepsis-induced increase in muscle MuRF1 and atrogin-1 (markers of proteolysis) as well as TNFα and IL-6 (inflammatory cytokines) mRNA was greater in DKO than WT mice." (PMID 24945486, 2014). "In all sepsis patients, there was a positive correlation between the interphase neutrophil number and plasma concentrations of IL-6 on the day of admission (day 0, r = 0.62, P = 0.002)." (PMID 25084831, 2014). "The plasma levels of MCP-1, IL-6, and IL-8 in the early death and survival groups were significantly different during the early stages of the sepsis episode." (PMID 24886652, 2014). "They found significantly higher levels of NE, NO, TNFα, IL-1β, IL-6, and IL-8 in neonates with early onset sepsis compared with controls." (PMID 24772418, 2014). "Pro-inflammatory cytokines such as TNF-α and IL-6 have been known to play a critical role in sepsis-induced inflammatory injury." (PMID 24896770, 2014). "Nor was there supernatant evidence that interphase neutrophils from sepsis patients produced cytokines (IL-2, IL-4, IL-6, IL-10, TNF or IFNγ) when cultured in vitro (unstimulated total cells or enriched CD66b + interphase neutrophils)." (PMID 25084831, 2014). "Cox regression analysis showed that cardiovascular disease, IL-6 and eHSPA12B level were correlated with prognosis of patients with severe sepsis." (PMID 24977412, 2014). "High levels of TNF-α, IL-6, and IL-1β in the BALF have been noted in patients with ALI/ARDS, and the persistent elevation of proinflammatory cytokines in humans with ALI or sepsis has been associated with more severe outcomes." (PMID 25013450, 2014). "Particular SNVs were in discussion regarding an association for sepsis (e.g. TNF, IL6, IL10) or having an potential bias to pathobiochemical processes of inflammation (e.g. SELE)." (PMID 25299518, 2014).
Sepsis (continued). "During the initial stage of sepsis, the rapid release of cytokines, that include TNFα, IL-1β, and IL-6, rapidly activate the acute phase response (APR) primarily in the liver leading to the production of acute phase proteins (APPs)." (PMID 24732911, 2014). "Previous study of group A streptococci showed that high levels of both TNF-α and IL-6 were inversely correlated with survival time in patients with sepsis." (PMID 25264876, 2014). "For example, Il-6 is up-regulated 31.1, 174.8 and 7.1 fold from control mice at two hours, one day, and three days, respectively, after the onset of CS sepsis." (PMID 24788351, 2014). "But in the Cox regression, IL-10 was excluded while IL-6 was demonstrated to be correlated to the prognosis of patients with severe sepsis." (PMID 24977412, 2014). "We found significant differences in IL-6 and IL-10 plasma levels between septic patients and healthy individuals (P<0.0001 for both) and between the sepsis and septic shock groups (IL-6:P=0.0036, IL-10:P=0.0096)." (PMID 25476907, 2014). "Synergically, TNF-α and IL-1 amplify the inflammatory signals by activating macrophages to produce proinflammatory cytokines such as IL-6 and IL-8, as well as lipid mediators and reactive oxygen species leading to sepsis-induced organ dysfunction." (PMID 25614712, 2014). "Serum IL-6 levels in elderly sepsis patients and aged septic mice were persistently higher than those in adult patients and young septic mice." (PMID 24962182, 2014). "MSCs have been shown to suppress production of pro-inflammatory cytokines and chemokines, including MIP-2(CXCL-2), CCL5, TNF, IL-6, and IL-1β, in animal models of lung injury and sepsis." (PMID 24423010, 2014). "Although we show a persistence of IL-6 and IL-10 elevations, their role in inflammation should be evaluated within the context of the stage of sepsis." (PMID 25182529, 2014). "Our group focuses on the paediatric population and previously demonstrated that interleukin 6 (IL-6) and bactericidal permeability increasing protein (BPI) polymorphisms are associated with different outcomes of sepsis." (PMID 24383711, 2014). "Presepsin levels had valuable diagnostic value for the diagnosis of sepsis, severe sepsis and septic shock at days 1, 3 and 8 of ICU treatment compared to PCT, IL-6, CRP and WBC." (PMID 25190134, 2014). "Upregulated IL-19 in sepsis induces lung and liver tissue injury by inducing apoptosis and the production of IL-6, IL-8, TNF-α, and reactive oxygen species (ROS)." (PMID 23710200, 2013). "In our study we have shown that IL-6 is a good indicator to evaluate the prognosis of neonates with sepsis." (PMID 23869218, 2013). "We also compared the performance of the IG count with CRP, LBP and IL-6, which are parameters commonly evaluated in patients with suspected infection or sepsis." (PMID 23398965, 2013). "Clinically relevant doses of PCT, similar to those achieved in sepsis, induced the secretion of the pro-inflammatory cytokines TNFα, IL-1β and IL-6 in whole human blood cells in vitro." (PMID 23937962, 2013). "Dexamethasone is the corticosteroid with the greatest anti-inflammatory activity, and inhibits the ex vivo production of TNFα, IL-6, IL-8, and IL-12p40 by LPS-stimulated whole blood from patients with sepsis in a dose-dependent manner." (PMID 24350219, 2013). "Rats in the CLP + BHT-H6 group had significantly higher survival rate (80%) and significantly lower levels of both IL-6 and IL-10 at 12 hrs postoperatively than those in the sepsis-control group." (PMID 23762108, 2013). "For example, it has been reported that the administration of anti-IL-6 antibodies improves survival in sepsis; while TNF blockade inhibits hepatic expression of iNOS and nitrotyrosine in mice with endotoxic shock." (PMID 23548047, 2013). "Similar to TNF-α, low or undetectable IL-6 serum levels are reported for some patients with severe bacterial infections, which limits its usefulness for ruling out sepsis and bacteremia." (PMID 23690657, 2013).
Sepsis (continued). "A significant increase in serum levels of IL-6, 8 and 10 provides a valuable marker for early diagnosis of sepsis and predicting outcome." (PMID 24570828, 2013). "TNF, as an endogenous pyrogen, is able to induce fever, induce apoptotic cell death, sepsis (through IL-1 and IL-6 production), cachexia and inflammation, as well as inhibit tumorigenesis and viral replication." (PMID 24137202, 2013). "Second, direct catalytic inhibition of ADAMTS13 by IL-6, a cytokine highly secreted in sepsis, has been reported in vitro using ULVWF strings secreted from human umbilical vein endothelial cells under flowing conditions." (PMID 24238574, 2013). "Persisting high levels of IL-6, in fact, correlate with poor outcome in sepsis, and its concentration correlates with the concentration of other inflammation markers." (PMID 23971020, 2013). "Since plasma levels of interleukin-6 (IL-6) and interleukin-10 (IL-10) were demonstrated as good parameters to predict the outcome of sepsis in our previous study, survival rate and plasma levels of IL-6 and IL-10 of rats were measured in the present study." (PMID 23762108, 2013). "Using ROC analysis we found the IG count a superior biomarker for sepsis compared to C-reactive protein, lipopolysaccharide binding protein and interleukin-6." (PMID 23398965, 2013). "TNF-α and IL-6 are cytokines elevated in sepsis both in humans and animals and their production is tightly related both to NF-kB activation and ROS levels." (PMID 24098806, 2013). "Recently, both IL-6 and IL-10 elevations were found to be significantly correlated with mortality of sepsis." (PMID 23762108, 2013). "Artesunate was able to protect mice subjected to sepsis by decreasing serum IL-6 and TNF levels via inhibition of Toll-like receptors expression and NF-κB activation in peritoneal macrophages." (PMID 24180288, 2013). "TNF-alpha induces monocytes to secrete other cytokines, such as IL-1, IL-6, and IL-8, which are essential for controlling infection and cleaning LPS from blood, and is also involved in sepsis and tissue lesions." (PMID 24130911, 2013). "In lung we observed an important increase in the IL-6 amount post sepsis in the groups of CLP-C and CLP-S compared to basal quantification." (PMID 24069301, 2013). "Inflammatory cytokines are necessary for limiting and eliminating local infections and increasing host survival, for example, IL-6 required for successful outcome in sepsis, given its ability to promote hepatocyte recovery and regeneration." (PMID 23762108, 2013). "TNF-α, IL-6 and IL-1β are the most important endogenous mediators in the sepsis process, the measurement of which can be helpful in the determination of sepsis severity." (PMID 24250599, 2013). "Meanwhile, several studies demonstrate that macrophages also produce IL-1β, TNF-α, and IL-6 during sepsis." (PMID 23675299, 2013). "IL-6 detects sepsis at an early stage of infection with a maximum of serum levels as early as 1-2 hours after inflammation reaction has started, potentially even prior to onset of clinical symptoms." (PMID 23431318, 2013). "IL-6, which plays a central role in the inflammatory process of sepsis and CAP, is also believed to affect MPV." (PMID 23497478, 2013). "Elevated IL-6 concentrations are measured in many acute conditions, such as burns, major surgery and sepsis, and peak subsequent to TNF-α and IL-1 concentrations." (PMID 23853427, 2013). "To verify sepsis after CLP procedure we measured IL-6 and TNF-α level in the serum as a marker for the systemic inflammation in septic and non-septic mice on the day of sacrifice." (PMID 24086305, 2013). "IL-6 was increased in the sepsis-control group and significantly decreased in the Pep 2.5-group compared to the sepsis-control group (P < 0.001)." (PMID 23302299, 2013).